IFITM2 (interferon induced transmembrane protein 2)
Diseases named in the same sentence as IFITM2 in open-access papers (continued):
Sharing a sentence is not in itself a finding about the gene and the disease.
schizophrenia (5 papers, 2007 to 2024). A major psychotic disorder characterized by abnormalities in the perception or expression of reality. "The genetic variant rs1,058,900 is located in an exon of IFITM2, whose role has been noted in schizophrenia." (PMID 36462729, 2023). "In particular, IFITM2, IFITM3, SERPINA3, and GBP1 showed increased mRNA levels in schizophrenia (p-values from qPCR ≤ 0.01)." (PMID 17822540, 2007). "As it has been suggested that schizophrenia may be the consequence of a vascular-inflammation, we studied the mRNA levels of SERPINA3, IFITM2, IFITM3, and GBP1 in a human endothelial cell line (TIME), before and after stimulation with TNF-α." (PMID 17822540, 2007). "Our results give additional support to the inflammatory hypothesis for schizophrenia and provide four biological markers for the disease likely to be directly involved in inflammatory processes, namely GBP1, SERPINA3, IFITM2, and IFITM3." (PMID 17822540, 2007). "Both these analyses confirmed that mRNA levels of SERPINA3, IFITM2, IFITM3 and GBP1 were increased in schizophrenia and were not simply the consequence of an infection immediately prior to death." (PMID 17822540, 2007).
breast carcinoma (3 papers, 2012 to 2025). "Whereas IFITM2 and TRIM34 have both been described to be induced by interferon but their role in carcinogenesis has not been studied, both LSP1 and PRKCDBP has been before associated with breast cancer." (PMID 23118876, 2012). "The heat map tables show the correlation between immune cell infiltrations and TNFAIP6, IFRD1, IFITM2, IFNGR1, IRF6, and NFIL3 in breast cancer." (PMID 39765744, 2024). "A non-significant difference was observed between IFITM2 gene expression and the clinical outcome concerning the relevance of immunological genes across breast cancer subtypes." (PMID 39765744, 2024). "Overall survival analysis showed that TNFAIP6, IFITM2, IFNGR1, and IRF6 expression levels were not significant, whereas IFRD1 (n = 568) indicated a significantly (p < 0.05) increased risk in Luminal A breast cancer patients, along with NFIL3 (n = 219) in Luminal B patients with similar significance." (PMID 39765744, 2024).
colorectal cancer (3 papers, 2017 to 2024). A primary or metastatic malignant neoplasm that affects the colon or rectum. "In this study, we demonstrated that interfering with IFITM2 expression inhibited the proliferative potential of colorectal cancer cells." (PMID 38802621, 2024). "We analyzed The Cancer Genome Atlas (TCGA) database for IFITM2 expression in colorectal cancer and used western blots to detect IFITM2 protein in specimens and cell lines of colorectal cancers." (PMID 38802621, 2024). "This study aim to investigate the expression of IFITM2 in colorectal cancer (CRC) and explore its effect on cell proliferation, migration, and invasion." (PMID 38802621, 2024). "We observed that tumor samples had upregulated IFITMs including IFITM1, IFITM2, and IFITM3, consistent with previous observations in colorectal cancer." (PMID 29088818, 2017).
glioma (3 papers, 2005 to 2024). A benign or malignant brain and spinal cord tumor that arises from glial cells (astrocytes, oligodendrocytes, ependymal cells). "In this study on glioma cells, the activation of numerous interferon-induced proteins (such as IFIT1, IFIT2, IFI27, IFITM1, IFITM2, and G1P2) lends support to this mechanism of pathogenicity." (PMID 15829208, 2005).
influenza (3 papers, 2015 to 2024). An acute viral infection of the respiratory tract, occurring in isolated cases, in epidemics, or in pandemics; it is caused by serologically different strains of viruses (influenzaviruses) designated A, B, and C, has a 3-day incubation period, and usually lasts for 3 to 10 days. "Specifically, influenza samples maintained higher levels of type I IFN response–associated antiviral ISGs (e.g., IFITM1, IFITM2, IFITM3, OAS2, OAS3, OASL) and antigen presentation genes (e.g., HLA-DRB5, HLA-C, B2M, HLA-B, HLA-E)." (PMID 34618691, 2021). "IFITM2 and IFITM3 code for interferon-induced transmembrane proteins, which are viral restriction factors that play a role in protecting cells against the entry of influenza and other viruses, as well as other aspects of interferon-signaling." (PMID 25905630, 2015).
pancreatic ductal adenocarcinoma (3 papers, 2017 to 2023). An infiltrating adenocarcinoma that arises from the epithelial cells of the pancreas. "Recently, it has been reported that pancreatic ductal adenocarcinoma cells are able to release BAG3 which activates macrophages via its binding to the receptor IFITM-2 (interferon-induced transmembrane protein 2)." (PMID 28680391, 2017). "Notably, another study identified IFITM2 as a receptor for a secreted form of the chaperone BAG3, showing that IFITM2 mediated signaling through PI3K and p38 MAPK pathways to promote tumorigenesis in a model of pancreatic ductal adenocarcinoma." (PMID 36435199, 2023).
renal clear cell carcinoma (3 papers, 2022 to 2024). "IFITM2 was reported to sustain tumor progression and lymphatic metastasis by inducing cytokines release, while migration and invasion were inhibited by the IFITM2 downregulation in renal clear cell renal carcinoma (ccRCC)." (PMID 36500393, 2022).
dengue (2 papers, 2021 to 2023). "In children and adults, gene ontology biological process (GOBP) terms calculated (p adj <= 0.05) using markers reflected increased interferon signaling in primary dengue, driven by increased expression of genes including IFITM2 and IRF4 in adults and GPX1 and TCEB2 in children." (PMID 37638019, 2023).
glioblastoma (2 papers, 2018 to 2024). The most malignant astrocytic tumor (WHO grade IV). "It has been recently reported that in U87 glioblastoma cells IFITM proteins inhibit HIV-1 entry in a co-receptor-dependent manner, that is, IFITM1 is more inhibitory on CCR5 tropic HIV-1 whereas IFITM2/3 confers a greater suppression of CXCR4 counterparts." (PMID 30087232, 2018).
HCMV infection (2 papers, 2019 to 2025). "Short hairpin RNA (shRNA) knockdown of IFITM1 alone or in combination with IFITM2 and IFITM3 inhibits HCMV infection as they are required for successful formation of the HCMV virion assembly complex (vAC) and production of infectious progeny virions." (PMID 31921100, 2019). "However, as with infection of MyD88-expressing cells, we observed that the UL88-STOP-mCh HCMV infection, in which MyD88 levels are higher, actually downregulated a number of antiviral ISGs, including IFITM1, IFITM2, IFITM3, MX1, and IFI16 (the nuclear sensor that plays a role in sensing of HCMV)." (PMID 40638072, 2025). "However, overexpression of IFITM1, IFITM2 and IFITM3 does not inhibit HCMV infection but rather results in a modest increase in the percentage of infected cells." (PMID 31921100, 2019).
lung adenocarcinoma (2 papers, 2022 to 2024). A carcinoma that arises from the lung and is characterized by the presence of malignant glandular epithelial cells. "Though IFITM2 has not been previously studied in lung cancer prognosis, the related IFITM1 was associated with poor survival in lung adenocarcinoma, contrary to the protective effect of IFITM2 observed in our study." (PMID 36303210, 2022).
melanoma (2 papers, 2014 to 2023). A malignant, usually aggressive tumor composed of atypical, neoplastic melanocytes. "Of note, IFITM2 expression is upregulated ensuing MITF silencing in melanoma cells (not shown) and deserves to be evaluated as a melanoma initiating cell surface marker." (PMID 25105565, 2014).
neuroblastoma (2 papers, 2016 to 2022). Neuroblastoma (NB) is the most common solid, extracranial childhood tumor. "The IFITM family (in humans, five IFITM members: IFITM1, IFITM2, IFITM3, IFITM5, and IFITM10; in mice, seven Ifitm members: IFITM1, IFITM2, IFITM3, IFITM5, IFITM6, IFITM7, IFITM10) was first discovered as interferon-induced genes in human neuroblastoma cells." (PMID 36012150, 2022).
acute coronary syndrome (1 paper, 2025). Signs and symptoms related to acute ischemia of the myocardium secondary to coronary artery disease. "This differential expression profile suggests a potential pathophysiological role for IFITM1 in post-infarction ventricular remodeling and heart failure development, whereas IFITM2/3 appear more broadly associated with acute coronary syndrome pathogenesis." (PMID 41368318, 2025).
allergic asthma (1 paper, 2023). A asthma with a basis in a pathological type I hypersensitivity reaction. "Interferon-induced transmembrane protein 3 (IFITM3), while unexplored in human allergic asthma, has been shown to drive and exacerbate Th2-cell responses in mouse studies, with genome studies linking IFITM2/3 variants to basophil counts and lung function." (PMID 38062491, 2023).
amyotrophic lateral sclerosis (1 paper, 2024). Amyotrophic lateral sclerosis (ALS) is a neurodegenerative disease characterized by progressive muscular paralysis reflecting degeneration of motor neurons in the primary motor cortex, corticospinal tracts, brainstem and spinal cord. "Neu_c4_RSAD2, Isg15_Neu, IFITM2_Neu, CCL6_Neu, and Cd34_mNeu were assessed as specific panels (OER10 > 83%, data was not shown) in anti-NMDA receiver encephalitis, which was significantly different from that of amyotrophic lateral sclerosis." (PMID 38319415, 2024).
autoimmune disease (1 paper, 2025). A disorder resulting from loss of function or tissue destruction of an organ or multiple organs, arising from humoral or cellular immune responses of the individual to their own tissue constituents. "Single-cell sequencing analysis of skin tissue from patients with juvenile dermatomyositis, which is an autoimmune disease, revealed a significant increase in the proportion of fibroblasts compared to normal tissue and increased IFITM2 expression in monocytes and myofibroblasts." (PMID 39428941, 2025).
bipolar disorder (1 paper, 2021). A disorder of the brain that causes unusual shifts in mood, energy, activity levels and the ability to carry out day-to-day tasks. "In addition, mRNA levels were higher in 71% (IFITM1) and 71% (IFITM2/3) of bipolar disorder subjects relative to their matched comparison subjects." (PMID 33436571, 2021).
Cirrhosis (1 paper, 2012). A chronic disorder of the liver in which liver tissue becomes scarred and is partially replaced by regenerative nodules and fibrotic tissue resulting in loss of liver function. "ATG16L2, DEFB114, FAM14B, IFNA21, IL8RB and KIR2DL genes were up-regulated in cirrhosis, whereas, FCRL3, IFITM2 and OAS2 genes were up-regulated in initial fibrosis." (PMID 22397681, 2012).
coronary artery disease (1 paper, 2025). "Notably, a recent genome-wide association study identified a genetic variant in IFITM2 (rs1059091) associated with an increased risk of CAD in an Indian population, providing the first genetic evidence linking the IFITM family to coronary artery disease." (PMID 41368318, 2025).
ductal carcinoma (1 paper, 2024). "A non-significant difference in IFITM2 expression between the tumor tissue and normal adjacent tissues was observed, which was correlated with immunochemical studies that showed negative in normal tissue compared to ductal carcinoma, where it was positive." (PMID 39765744, 2024). "However, IFITM2 protein expression was negative in normal tissue compared to ductal carcinoma (positive)." (PMID 39765744, 2024).
inflammatory bowel disease (1 paper, 2025). A spectrum of small and large bowel inflammatory diseases of unknown etiology. "Cluster 6 was characterized by the expression of the IFN-γ–induced genes Ifitm1, Ifitm2, and Ifitm3, which have been reported to be associated with inflammatory bowel diseases, alongside with the integrin Itgb1." (PMID 40924026, 2025).
Lymphatic Metastasis (1 paper, 2021). Transfer of a neoplasm from its primary site to lymph nodes or to distant parts of the body by way of the lymphatic system. "Interferon-induced transmembrane protein 2 (IFITM2), an inflammation related gene was reported to be associated with lymphatic metastasis and poor clinical outcome." (PMID 35096589, 2021).
metastasis (1 paper, 2022). The spread or migration of cancer cells from one part of the body (where they first appeared) to another. "IFITM2 is associated with lymphatic metastasis and poor clinical outcomes." (PMID 35204406, 2022).
multiple sclerosis (1 paper, 2024). A progressive autoimmune disorder affecting the central nervous system resulting in demyelination. "We further describe the first single-cell eQTL analysis of CSF and identify two eQTLs in CD8+ T cells correlated with multiple sclerosis susceptibility, both in genes related to controlling viral responses—ZC3HAV1 and IFITM2." (PMID 38038362, 2024). "Of particular interest were two expression quantitative trait loci in CD8+ T cells that were fine mapped to multiple sclerosis susceptibility variants in the viral control genes ZC3HAV1 (rs10271373) and IFITM2 (rs1059091)." (PMID 38038362, 2024). "In three instances, the credible set for the eQTL included the known multiple sclerosis susceptibility variants: rs3764021 for the expression of CLECL1 in macrophages; rs1059091 for the expression of IFITM2 in CD8+ T cells; and rs10271373 for the expression of ZC3HAV1 in CD8+ T cells." (PMID 38038362, 2024).
myeloma (1 paper, 2022). "Highly expressed IFITM2 participates in the type I interferon response to protect cells from viral pathogens and activates the expression and secretion of IL-6, which promotes the differentiation of B cells into plasma cells, mediating the growth of myeloma and stimulating bone resorption." (PMID 36131282, 2022).
nephritis (1 paper, 2023). Inflammation of renal tissue. "IFITM2 and IFITM3 showed up-regulation in urine PTCs, suggesting their potential as nephritis markers." (PMID 38077419, 2023).
pancreatic cancer (1 paper, 2020). "Based on these results, secreted BAG3 (and its receptor IFITM-2) represent potential clinical candidate molecules for the treatment of pancreatic cancer (development of an anti-BAG3 humanized antibody for treatment of pancreatic cancer)." (PMID 32121220, 2020).
psoriasis (1 paper, 2019). An autoimmune condition characterized by red, well-delineated plaques with silvery scales that are usually on the extensor surfaces and scalp. "The psoriasis-associated supersets were also found to be closely linked in the blood network via KDs such as CTSH, IL1B, STAT1, and IFITM2." (PMID 30642337, 2019).
renal carcinoma (1 paper, 2022). A carcinoma arising from the epithelium of the renal parenchyma or the renal pelvis. "IFITM2 upregulation is associated with shorter survival of patients with gastric or renal cancer." (PMID 36466909, 2022). "However, recent studies have documented protumorigenic effects of IFITM2 on gastric and renal cancer in vivo and in vitro." (PMID 36466909, 2022).
reovirus infections (1 paper, 2020). "We further analyzed the proteomic data of in vivo reovirus infections and, interestingly, found that classical reovirus and NDRV infections significantly upregulated the expression of RIG-I, MDA5, IRF3, and several ISGs, such as Mx, viperin, IFIT5, and IFITM2 in both the liver and spleen." (PMID 33344524, 2020).
Sjogren syndrome (1 paper, 2022). An autoimmune disorder in which immune cells attack and destroy the glands that produce tears and saliva. "Additionally, genes related to type I-IFN activity including, ICSBP1, MX1, IFITM1, IFITM2, IRF9, were found to be overexpressed in patients with Sjogren’s syndrome." (PMID 36059459, 2022).
Stroke (1 paper, 2022). Sudden impairment of blood flow to a part of the brain due to occlusion or rupture of an artery to the brain. "We next examined the expression profile of IFITM family members (Ifitm1, Ifitm2, and Ifitm3) in the post-stroke brain of aged mice." (PMID 36012150, 2022).
infection (53 papers, 2007 to 2025). The state of being infected such as from the introduction of a foreign agent such as serum, vaccine, antigenic substance or organism. "The infection of HeLa cells with influenza virus showed that a decrease in the expression of IFITM2 or IFITM3 increased the cell susceptibility to the virus by about two or four times, respectively, compared with control cells." (PMID 35216030, 2022). "Thus, it is tempting to speculate that this VOC did not only evolve reduced susceptibility to IFN inhibition but may also be less dependent on IFITM2 for efficient infection than other SARS-CoV-2 variants." (PMID 35543509, 2022). "We observed that Ifitm1, Ifitm2, Ifitm3, Ifitm5 and Ifitm6 were highly upregulated during NF1_LV infection while only Ifitm1, Ifitm3, Ifitm6 were upregulated during NF45_HV exposure and at a lower level." (PMID 39735262, 2024). "The Omicron variant had decreased cleavage efficiency in certain cell types and increased susceptibility to IFITM2 and IFITM3, possibly contributing to the milder disease states seen with Omicron infections." (PMID 37985854, 2024). "For IAV, the overexpression of IFITM2 and IFITM3 was associated with a significant reduction in infected cells at 8 h post-infection (assessed by intracellular staining for the viral nucleoprotein (NP) protein,)." (PMID 37111405, 2023). "In agreement to our previous study, treatment with antibodies directed against ACE2 or the N-proximal region of IFITM2 inhibited infection by the NL-02-2020 strain, while an isotype control antibody had no significant inhibitory effect." (PMID 35543509, 2022). "The ability of SARS-CoV-2 to hijack IFITM proteins (especially IFITM2) for efficient infection seems to require specific interactions between the N-terminal portion of IFITMs and the viral Spike protein." (PMID 35543509, 2022). "Ectopic expression of IFITM2 inhibited infection and partially restored sensitivity to temsirolimus, while the combination of IFITM2 and IFITM3 restricted infection further and fully restored temsirolimus sensitivity." (PMID 33880473, 2022). "Here, we show that depletion of endogenous IFITM2 expression almost entirely prevents productive infection of Alpha, Beta, Gamma, Delta, and Omicron SARS-CoV-2 VOCs in human lung cells." (PMID 35543509, 2022). "Infection experiments showed that peptides corresponding to the N-proximal region of IFITM2 that is recognized by the SARS-CoV-2 inhibiting IFITM2 antibody antibodies also efficiently impair SARS-CoV-2 replication." (PMID 34321474, 2021). "We found that infection of IFITM2-Y19F cells was slightly enhanced compared to that of IFITM2 cells." (PMID 33563656, 2021). "Already at 6 h post-infection, depletion of IFITM2 significantly reduced the intracellular levels of viral RNA." (PMID 34321474, 2021). "At 24 h post-infection, silencing of IFITM2 expression decreased intracellular SARS-CoV-2 RNA levels by ~15-fold and extracellular viral RNA yield by ~5-fold." (PMID 34321474, 2021). "This included IFITM1 and IFITM2, which are known to inhibit the infection and replication of respiratory syncytial virus, IFI27, a known biomarker for RSV29, and IRF7, a gene associated with suppression of innate immunity response." (PMID 31554845, 2019). "Compared with the control shRNA targeting luciferase, the specific shRNAs caused decreased expression of IFITM1, IFITM2, or IFITM3 after ATMUV infection, respectively." (PMID 28473814, 2017). "In DENV-2 infected cells, viral RNA replication resulted in a 24-fold increase in IFN-β mRNA between 24 and 48 h post infection, which was accompanied by a 7-fold increase in IFITM2 mRNA." (PMID 24992036, 2014). "Little is currently known regarding the relationships between CVB and IFITMs; however, our data suggest that IFITM2/3 may support infection." (PMID 39772131, 2024). "In the absence of infection in the four patients, it is conceivable that IFITM2 and IFITM3 are implicated in aseptic inflammation and cell detachment of PTCs." (PMID 38077419, 2023).